LEP (leptin)
Diseases named in the same sentence as LEP in open-access papers (continued):
Sharing a sentence is not in itself a finding about the gene and the disease.
Insulin resistance (continued). "Additionally, in chronic heart failure insulin resistance is related to hyperleptinaemia This might explain the significant but clinically only irrelevant small improvement of HbA1c during leptin therapy in diabetic patients in a previous study." (PMID 37176525, 2023). "The loss of leptin signaling independent of the Mc4r pathway or the more pronounced hepatic insulin resistance in ob/ob mice may also affect the turnover of the TCA cycle." (PMID 37681411, 2023). "The potential mechanisms underlying VAI and FPG might include the following aspects: Excessive visceral fat promoted the secretion of increased inflammatory adipokine, including IL-6 and leptin, which might contribute to the occurrence of insulin resistance and diabetes." (PMID 36774500, 2023). "Furthermore, leptin secretion is stimulated by increased insulin levels, which could be a contributing mechanism in the present study for women with slight insulin resistance." (PMID 37731394, 2023). "Therefore, this emerging and promising biomarker has shown a more prominent correlation not only with insulin resistance than the evaluation of leptin and adiponectin alone has, but also demonstrates a remarkable reduction compared to the higher number of metabolic risk factors." (PMID 37571250, 2023). "Also, women have higher levels of leptin and adiponectin, which are important adipokines in regulating food intake and energy expenditure and can also contribute to the development of peripheral insulin resistance." (PMID 37763285, 2023). "We hypothesized that administration of NAC, an antioxidant that contains sulfur, may aid in weight reduction in these individuals by regulating energy-related genes and hormones including leptin and adiponectin, as well as lowering insulin resistance and the anti-inflammatory pathway." (PMID 37794966, 2023). "Thus, we conclude that TNF-α disrupts the regulation of leptin on the β cell GSIS function by inhibiting leptin receptor LepRb and thus producing excessive insulin secretion related to hyperinsulinemia, which is postulated to be a cause of insulin resistance." (PMID 35198097, 2022). "The goal of the study was to examine if there was a link between the leptin (LEP)/leptin receptor (LEPR) gene polymorphism and insulin resistance in pregnant women, and to determine the extent to which the leptin gene polymorphism could cause insulin resistance." (PMID 36128550, 2022). "The present findings that higher levels of leptin and greater insulin resistance cluster together with lower hippocampal functional cohesiveness and integration suggest that hippocampal “hypoconnectivity” may represent an early sign of hippocampal distress that predates cognitive dysfunction." (PMID 35492025, 2022). "The mechanisms implicated in the greater renal beneficial effects induced by the simultaneous administration of PRL and EMPA remain unknown but an improvement in insulin resistance and a reduction in leptin and renal inflammatory cytokine levels could be involved." (PMID 35119333, 2022). "This influence may be a manifestation of leptin and insulin resistance in the immune system." (PMID 35406000, 2022). "In addition, compared to subjects with an abundant microbiome, subjects with low richness in the gut microbiome had higher levels of C-reactive protein, leptin, dyslipidemia, insulin resistance, and inflammatory phenotypes, and gained more body weight and body fat." (PMID 36079841, 2022). "They concluded that increased leptin levels could predict insulin resistance in obese patients." (PMID 36293132, 2022). "However, calling these mechanisms “leptin resistance” may lead us to believe the failure to respond as leptin arises as a pathological response akin to “insulin resistance”—the pathological failure to respond to insulin." (PMID 36394061, 2022).
Insulin resistance (continued). "Although some studies have suggested that decreased leptin and subsequent insulin resistance might be the reasons for hepatic steatosis induced by CLA, leptin deficiency in the ob/ob mice did not aggravate lipid accumulation in the OB-CLA group, which was similar to a previous study." (PMID 35382379, 2022). "Studies involving both obese humans and rodents showed that leptin resistance may have a direct contribution to the reduction of lipid oxidation in organs sensitive to insulin, which may lead to lipid accumulation and insulin resistance." (PMID 35386146, 2022). "The results indicated that administration of EPS103 could alleviate insulin resistance, reduce the levels of fasting blood glucose, glycosylated hemoglobin A1c, leptin and fasting serum insulin, improve glucose tolerance, protect pancreas and liver, and modulate blood lipid disorders." (PMID 36429163, 2022). "The observed inverse associations of birth weight with subsequent CVD risk in adulthood may reflect shared mechanistic pathways in utero where metabolic stress leads to insulin resistance, decreased leptin levels, and altered intracellular insulin signaling pathways." (PMID 35875812, 2022). "We examined insulin and leptin signaling pathways in the hippocampus and cortex to assess whether GMT ameliorated brain insulin resistance and leptin resistance, given that these pathways play key roles in maintaining blood glucose homeostasis and brain function." (PMID 35721013, 2022). "Therefore, dysregulation of the adipo-insular axis could be a result of leptin resistance in the pancreatic cells, hence contributing to the development of insulin resistance and type 2 diabetes." (PMID 36381191, 2022). "Leptin could improve insulin sensitivity and reduce insulin resistance." (PMID 36092166, 2022). "The existence of “leptin-resistance,” akin to “insulin-resistance”, has been hypothesized on the basis that humans with high levels of leptin as well as large fat deposits appear to resist the hunger-damping signals of leptin." (PMID 35327470, 2022). "Downregulation of CRP, TNF-α, and nitrites and upregulation of adiponectin could be responsible for LTBI mediated protection against insulin resistance (IR), while the high levels of IL-1β, IL-12, and leptin could be responsible for IR mediated anti-TB immunity." (PMID 35832818, 2022). "Importantly, a decrease in leptin-reacting immunoglobulin affinity kinetics may also be related to hyperinsulinemia, insulin resistance, and leptin resistance in patients with type 2 diabetes." (PMID 33953692, 2021). "Furthermore, the positive relationship of leptin with insulin resistance and uric acid levels and the inverse relationship with renal function may contribute to this vascular damage." (PMID 34385686, 2021). "Diabetic subjects might benefit from correction of leptin resistance as well as insulin resistance." (PMID 34446063, 2021). "Consequently, Leptin/Adiponectin relation (LAR), a ratio that has been directly linked to situations of insulin resistance and metabolic syndrome disease, turned out to be higher in both groups of pregnant rats whose mothers had consumed fructose during pregnancy in comparison to CC dams." (PMID 34684668, 2021). "Elevated leptin levels activate Kupffer cells and liver stellate cells, which give rise to the inflammatory processes in the liver, In contrast, adiponectin exerts anti-inflammatory properties in the liver and improves hepatic and peripheral insulin resistance." (PMID 34593018, 2021). "However, it was observed that overnutrition-mediated activation of IKKβ/NF-κB was activated intracellularly by ER stress and prompted both hypothalamic leptin and insulin resistance through the induction of suppressor of cytokine signaling 3 (SOCS3), an inhibitor of leptin and insulin signaling." (PMID 34957242, 2021).
Insulin resistance (continued). "The positive correlation between baseline leptin and PP changes over time was also confirmed in the linear regression analysis adjusted for baseline age, PP value, excess body weight, renal function, smoking, physical activity, alcohol consumption, hypolipidemic therapy and insulin resistance." (PMID 34385686, 2021). "Higher leptin levels were found in macrosomic newborns and are related to insulin levels and adiposity; this may explain how fetuses of obese mothers develop insulin-resistance in the womb and are born with higher adiposity." (PMID 33424775, 2020). "Therefore, we think that phloretin may improve blood sugar levels by regulating the levels of leptin and adiponectin, improving insulin resistance in obese mice." (PMID 33014333, 2020). "We speculate that it can be associated with subclinical insulin resistance and hyperinsulinemia independent of adiposity, since an altered adipokine profile (high level of leptin and low level of adiponectin) leads to metabolic derangements." (PMID 32512860, 2020). "Lower adiponectin and leptin levels may contribute to insulin resistance." (PMID 32336076, 2020). "In addition, the development of leptin resistance due to insulin resistance in diabetic and adipose patients may contribute to a rather reduced leptin effect." (PMID 32685095, 2020). "In addition, decreased insulin resistance can lead to lower levels of proinflammatory cytokines, including tumor necrosis factor-alpha, interleukin-6, leptin, and chronic hepatic inflammatory markers, which have been associated with liver diseases including liver cancer." (PMID 33271947, 2020). "Regarding adiponectin and leptin, our finding showed that a diet with low AGEs content could significantly increase adiponectin and decrease leptin levels, two important markers of insulin resistance, suggesting that diet derived AGEs also have effects on insulin sensitive tissues." (PMID 33335235, 2020). "Furthermore in the Hoorn study, insulin resistance was a main determinant of leptin levels." (PMID 32131811, 2020). "Further, since the association between leptin and incident type 2 diabetes was found in men but not in women and this association was mediated by insulin resistance, the relationship is likely a function of visceral obesity that resembles the body shape of men rather than women." (PMID 32131811, 2020). "In conclusion, in our African American sample, adiponectin was inversely associated with incident type 2 diabetes, while leptin’s direct association with diabetes was mediated by insulin resistance and present only among men and abdominally non-obese participants." (PMID 32131811, 2020). "In addition, adiponectin can reverse insulin resistance in mice in combination with leptin." (PMID 32542027, 2020). "Interestingly, it has also been demonstrated how this increase in leptin levels and a higher ratio with adiponectin are associated with an increase in the proinflammatory cytokines like TNF-α and IL-6, once again related to the insulin resistance and T2DM." (PMID 32917030, 2020). "Thus, it is possible that increasing the production of cytokines in response to zinc supplements, with is the mechanism responsible for increasing the amount of leptin, leads to a decrease in blood glucose and insulin resistance in 75 and 175 mg/kg treatment groups." (PMID 32405346, 2020). "Consequently, improvement of leptin and insulin resistance by hesperidin treatment alone and/or in combination with orlistat might be in part by improvement in serum and tissue levels of leptin and insulin respectively as found in results." (PMID 31929574, 2020). "Another putative mechanism linking insulin resistance in DM1 could involve leptin signaling." (PMID 31849810, 2019).
Insulin resistance (continued). "The aim of our research was to determine whether regular exposure of the whole body to cryogenic temperatures has an effect on changes in glucose, asprosin, and other hormones related to metabolism (leptin, adiponectin, irisin) and insulin resistance in menopausal women with metabolic disorders." (PMID 31510055, 2019). "Lastly, serum leptin concentrations were enriched for the GO term G-protein-coupled receptor activity, which have been found to be directly involved in pancreatic β-cell destruction and insulin resistance and remain potential targets for drug therapy for metabolic syndrome and type II diabetes." (PMID 31698676, 2019). "Moreover, serum BSP concentrations did not correlate with the patients’ body mass index (BMI) or markers for a deregulated metabolic state (serum levels of Adiponectin, Leptin, leptin receptor) or insulin resistance (serum levels of Insulin, C-peptide, HbA1c, HOMA)." (PMID 29950701, 2018). "In addition, XBP1s abolished palmitate-induced insulin resistance in adipocytes by increasing adiponectin secretion, repressing the secretion of pro-inflammatory adipokines such as leptin, monocyte chemoattractant protein 1, and tumor necrosis factor α, and decreasing fatty acid release." (PMID 30111834, 2018). "Expectedly, plasma leptin levels correlated with anthropometric parameters in all participants and individual groups as well as with insulin levels, homeostasis model assessment of insulin resistance (HOMA-IR) and beta cell function (HOMA-β) in the total cohort." (PMID 29795184, 2018). "Similarly, leptin/MCP-1 index could be an additional indicator for insulin resistance/sensitivity when compared to HOMA-IR (AUC = 0.72) and QUICK (AUC = 0.73)." (PMID 29785210, 2018). "One possibility is that insulin resistance is one of many factors affecting sleep disordered breathing and requires coincident impairments in the autonomic nervous system, glycemic control, or others (see leptin in the following section) to generate the conditions necessary for promoting OSA." (PMID 30127766, 2018). "Furthermore, adiponectin reduces insulin resistance while leptin enhances insulin resistance." (PMID 28893239, 2017). "Thus, inflamed adipose tissue could promote low-grade systemic inflammation by releasing proinflammatory cytokines and chemokines (IL-1ß, TNF-α, IL-6, leptin, CCL2, CCL3, and CXCL8) and causing insulin resistance and endothelial dysfunction." (PMID 28512338, 2017). "The leptin/adiponectin ratio is a surrogate marker of adipose tissue function, and higher ratios are associated with a dysfunctional phenotype that contributes to inflammation and insulin resistance in nondiabetic individuals." (PMID 28642810, 2017). "However, the statistically significant inverse associations of serum adiponectin and leptin with β-cell function disappeared after additional adjustment for insulin resistance (data not shown)." (PMID 28786989, 2017). "No previous study has examined the association between leptin, an adipokine, and the risk of frailty in older adults, and whether this association could be explained by insulin resistance or chronic inflammation." (PMID 28400989, 2017). "Inflammation pathways were coordinately up-regulated with insulin resistance and adipokines, e.g., the chemokine signaling pathway correlated with insulin sensitivity (Matsuda index) (r = −0.807), fs-insulin (r = 0.858), fs-adiponectin (r = −0.598) and leptin (r = 0.428) (p < 0.001 for all)." (PMID 27080554, 2016). "ER stress may therefore play a key role in leptin and insulin resistance." (PMID 27812350, 2016). "A reduction in leptin sensitivity may reduce cytokine-induced inflammation and insulin resistance." (PMID 27703473, 2016).
Insulin resistance (continued). "Downstream effects from insulin resistance, whether peripheral or central, could involve increased glucose and advanced glycation end products (AGEs), and alterations in adipokines (e.g., leptin) and other factors (Cherbuinet al., 2012;Holdenet al., 2009;Yaffeet al., 2011)." (PMID 27303627, 2016). "Thus, AnK prevented HFD-induced abnormalities in leptin levels and improved insulin resistance." (PMID 27242912, 2016). "In the present study, subjects with insulin resistance showed higher body fat percentage than their controls, therefore, the inhibitory effect of leptin on adipose FNDC5 expression may also explain the decreased circulating irisin in subjects with insulin resistant." (PMID 27473122, 2016). "Accordingly, the insulin resistance biomarkers such as serum insulin, leptin, adiponectin, retinol binding protein 4 (RBP4) and lipid profile were assayed, and the underlying transcriptomic changes induced by C.nutans on hepatic insulin resistance-related genes were evaluated." (PMID 26924713, 2016). "High level of serum leptin could increase insulin resistance." (PMID 26000008, 2015). "Genetic polymorphisms linked to T2D have been identified in at least 3 dozen genes, most of which influence both hepatic and peripheral insulin resistance, and adipogenesis as well as beta cell mass and function; however, no mutations in leptin signaling have been identified in human T2D." (PMID 25961053, 2015). "However, the higher leptin levels could also represent a state of leptin resistance contributing to insulin resistance." (PMID 26244048, 2015). "A decrease in serum leptin levels following non-surgical periodontal treatment has been reported, which could be associated with a decrease in insulin resistance in the obese population." (PMID 25662559, 2015). "It was suggested that insulin resistance to leptin in β-cells in glucose intolerance state, might prevent the inhibitory effect of leptin on insulin secretion resulting in hyperinsulinemia, which might exhaust pancreatic β-cells leading to development of NAFLD." (PMID 26569494, 2015). "Finally, we hypothesized that metabolic satiety parameters such as leptin and insulin resistance exert a mediating effect on this relation, indicating an impaired interaction between homeostatic and mesolimbic reward pathways and increasing BMI." (PMID 25368558, 2014). "Moreover, an elevated serum leptin level is known to correlate closely with insulin resistance." (PMID 24879081, 2014). "Since they have excess adipose tissue, obese individuals generally have higher levels of leptin but, similar to the insulin resistance that is associated with type II diabetes, they do not exhibit a normal satiation response due to changes in the leptin detection circuit." (PMID 25339940, 2014). "Expression of Ctrp2 transcript is up-regulated in young (8-week-old) but not older (12-week-old) leptin-deficient ob/ob mice; this is thought to be a compensatory response to leptin deficiency prior to the development of morbid obesity and severe insulin resistance." (PMID 24586339, 2014). "This increase in the susceptibility to overconsumption in obese individuals may be related to increased leptin and insulin resistance (resulting from the excessive accumulation of adipose tissue), which may reduce the sensitivity of short-term appetite control." (PMID 24734042, 2014). "Nevertheless, some predictable mechanisms through which hypertension were prompted might be the unfavourable effects of changes, such as insulin resistance and elevation of cholesterol and leptin levels, which have been observed in obese persons with blood pressure." (PMID 25395911, 2014). "Several mediators such as leptin, which reduces insulin-induced fatty acid oxidation and triacylglycerol synthesis, or fatty acids, which compete with glucose for their mitochondrial oxidation, are commonly suggested as contributors of insulin resistance and glucose intolerance." (PMID 25142225, 2014).